CCL2 (C-C motif chemokine ligand 2)
Diseases named in the same sentence as CCL2 in open-access papers (continued):
Sharing a sentence is not in itself a finding about the gene and the disease.
tumor (continued). "A total blockade of CCL2 both from the tumor and the stroma decreased recruitment of CCR2+ monocytes, inhibited tumor metastasis and extended survival time of tumor-bearing mice." (PMID 29934505, 2018). "Similar to CCL2, CXCL12 recruits immune suppressive myeloid cells to the tumor site-especially MDSC." (PMID 30126117, 2018). "In four different mouse tumor models, trabectedin significantly inhibited the production of cytokines including CCL2 and IL6, which are important in promoting tumor growth." (PMID 29594035, 2018). "FOXC1 is also associated with the IL-8 signaling pathway and the transactivation of genes responsible for tumour angiogenesis and metastasis, CXCR2 and CCL2." (PMID 29487724, 2018). "It is interesting that while IL-1β, CCL2, and VEGF are secreted at high levels from hypoxic and/or MSCs-entrained IRISOE TNBC tumor cells, their receptors, IL-1R, CCR2, and VEGFR2 were only observed on MSCs, TAMs, and ECs, respectively." (PMID 29262555, 2017). "The increase in IL-6, IL-12, CCL2, CCL3, CCL5, CXCL9 levels would a priori predict for elevated levels of M1 type macrophages in the tumor, which independently validates our prior IHC staining findings." (PMID 29137331, 2017). "This strategy translated into improved homing (>10 fold) to CCL2-secreting neuroblastoma compared to CCR2-negative T cells, as well as greater in vivo anti-tumor activity." (PMID 28331613, 2017). "CCL2 had an equal effect on CD206+ and MHCII+ populations of macrophages, thus balancing the pro- and anti-tumor macrophage cell population." (PMID 28143493, 2017). "Chemokines and cytokines including CCL2, CXCL12, CSF1, CCL5, CCL22, IL6 and TGFB3 are secreted by primary tumor cells to recruit immune cells to escape from anti-tumor immune responses." (PMID 28591712, 2017). "Whereas, the arrival of TANS perpetuates a sustained release of CCL2, GM-CSF, CCL17 which correspond to elevated tumor size, microvascular invasion and inward migratory activity of the macrophages and Tregs." (PMID 28441391, 2017). "For example, CCL2 blocking agents, which prevent monocyte recruitment to the tumor and subsequent generation of monocyte-derived TAM, have been shown to impair tumor progression in several tumor models." (PMID 28360914, 2017). "Expression of tumor-induced factors responsible for MDSCs’ differentiation and proliferation, such as, TGFβ, MMP9, IL-6, VEGF, CXCR4, CCL2 was upregulated in MDSCs from CD8 depleted NLGP immunized mice, that was in downregulation after NLGP treatment." (PMID 28414726, 2017). "Although these experiments identify host cell expression of CCR2 and tumor cell expression of TRAIL-R and CCL2 as required for this pro-tumorigenic crosstalk between the TRAIL/TRAIL-R and CCL2/CCR2 systems, the source for TRAIL can be many fold." (PMID 28212753, 2017). "The altered expression of CCL2 and CCR2 was found in NSCLC cells and was correlated with sex, smoking habits, histology and tumor size." (PMID 28424406, 2017). "TRAIL-R suppression in tumor cells impaired CCL2 production and diminished both lung MDSC presence and tumor growth." (PMID 28212753, 2017). "Additional reported data suggested that CCL2 induced EMT through the activation of STAT3 signals and inhibited STAT3 signaling to reduce the invasiveness of tumor cells." (PMID 28757590, 2017). "Chemotactic molecules such as CCL2, SCF-1, and VEGF derived from tumor cells or stromal cells mediate macrophage mobilization into tumor tissues." (PMID 28848446, 2017). "Several cytokines, such as CCL2, CCL21, VEGF and CXCL1 are present at high levels in the tumor microenvironment and known to be involved in tumor growth promotion, vascular development, and evasion of antitumor immunity." (PMID 28969039, 2017). "In line with our results implicating FADD as crucial for TRAIL-R-mediated CCL2 secretion, 3LL FADD KO cells replicated our results observed in CCR2 KO mice regarding tumor burden and myeloid infiltrates." (PMID 28212753, 2017).
tumor (continued). "In accordance, the receptor of CCL2, CCR2, is required to facilitate increased MDSC presence and tumor growth." (PMID 28212753, 2017). "In tumors, chemokines such as CCL2, CCL5, IL-8, and CXCL-12 also chemoattract TAMs to the tumor site." (PMID 28545495, 2017). "Serum CCL2, IL-10, IL-5, IL-4, TNF-α, IL1-β and IL-12p70 levels increased with age irrespective of parity status, but were specifically reduced following OC tumor induction only in multiparous mice." (PMID 28966800, 2017). "Within the molecules that are increased in the tumor microenvironment, glutamate and immune factors such as TNF-α, IL-1α, and CCL2 should be taken into special consideration." (PMID 29163208, 2017). "In tumor-bearing mice, the CCR2-receptor is highly expressed by most MDSC subsets, and CCL2 alone is sufficient to induce migration of MDSCs." (PMID 28498847, 2017). "This was, for instance, the case with CCR5 which, with the two ligands i.e. CCL2 and CCL3, formed the two ligand-receptors pairs that exhibited the largest increase in correlation when comparing tumor to normal tissues." (PMID 28821810, 2017). "These evidences further verify that CCL2/CCR2 signaling is involved in the tumor microenvironment, which explained why l-CDL decreased the volume of tumor and diminished angiogenesis, and alleviated the TCIP after sciatic nerve injury." (PMID 28587280, 2017). "Of note, CCL2- and/or VEGFA-neutralizing antibodies administered to BALB/c athymic nude mice bearing pre-established lung tumors drastically reduce tumor growth, angiogenesis, TAM accumulation, and tumor metastasis." (PMID 28851377, 2017). "In aggressive malignancies, metastatic MAMs arrive at secondary sites and in turn recruit inflammatory CCR2 bearing monocytes by CCL2, which in themselves release CCL3 and express CCR1, amplifying tumor potential." (PMID 28441391, 2017). "TAM derive from circulating monocytes, which are recruited into the substance of the tumor by a wide range of chemokines, especially MCP-1/CCL2, CXCL1, CXCL10 and SDF-1/CXCL12, released either by tumor cells or other stromal cells." (PMID 28098760, 2017). "TAMs originate from circulating monocytes, which are recruited to the tumor microenvironment and reprogrammed by tumor-derived factors such as S1P, colony-stimulating factor-1, VEGF-A, and CC chemokine ligand 2 (CCL2)." (PMID 28804221, 2017). "CCL2 contributes towards this initial stage, guiding cancer cell migration by interacting with the CCR2 receptor expressed on tumor cells." (PMID 26885690, 2016). "Among them, MCP-1 (CCL-2), IL-1b, IL-6, TNF-α were especially shown to be involved in the recruitment of immature cells into tumor microenvironment." (PMID 27993141, 2016). "CCL2, also named as monocyte chemotactic protein 1 (MCP1), was produced by stromal components in the tumor microenvironment and tumor cells." (PMID 27888616, 2016). "CCL2 expression in CRC cells and TAM accumulation are strongly correlated with advanced tumor stages and a poor prognosis." (PMID 27136535, 2016). "I.p. delivery of anti-CCL2, anti-VEGFA and anti-CCL2/VEGFA combination dramatically reduced lung tumor growth, angiogenesis, TAMs accumulation, and tumor metastasis in mice." (PMID 27541266, 2016). "CCL2, CXCL1 and CXCL2 expressed by IECs, stromal and tumor cells during CRC possess pro-tumoral capacities since they chemoattract myeloid cells including neutrophils and tumor-associated macrophages, and stimulate angiogenesis." (PMID 27344176, 2016). "This suggests that the CCL2/CCR2 axis promotes tumor growth in the MMTV-neu model and genetic disruption of Ccr2 promotes tumor growth through other pathways." (PMID 27820834, 2016). "Here we demonstrate that RT stimulates increased production of two chemokines, CCL2 and CCL5, at the tumor site." (PMID 27852031, 2016). "Here, we determine that both the CCL2:CCR2 and CCL5:CCR5 chemokine axes are uniquely modulated by RT in various tumor models." (PMID 27852031, 2016).
tumor (continued). "CCL2 has been reported to function as a chemo-attractant, and VEGFA is an important cytokine involved in angiogenesis and tumor growth." (PMID 27541266, 2016). "Taken together, our data suggest that radiation not only activates the STING pathway to induce Th1/Tc1 T cell activation but also activates the canonical NF-κB to increase CCL2 and CCL5 to induce Th1/Tc1 T cell tumor infiltration." (PMID 27014915, 2016). "It has been reported that CCL2 and its primary receptor CCR2 have the ability to recruit monocyte from peripheral blood to tumor site regulate the mobilization of macrophages." (PMID 27409666, 2016). "CCL2 binds the cognate receptor CCR2, and together this signaling pair has been shown to have multiple pro-tumorigenic roles, from mediating tumor growth and angiogenesis to recruiting and usurping host stromal cells to support tumor progression." (PMID 26885690, 2016). "Our data support an essential role of TAMs within the chemokine network, since they express 11 CCL members and three CCR receptors, of which two (CCL2 and CCL5) are also expressed by tumor cells." (PMID 27215396, 2016). "Further, experimental models of cancer have shown that gene therapy with CCL2 and CX3CL1/fractalkine can stimulate tumor rejection by increased infiltration and activation of NK cells." (PMID 27148255, 2016). "Microarray analysis of the tumors revealed that targeting STAT3 increased the expression of multiple chemokines, such as CCL2, CCL9, CCL12, CCL17, and CCL21c, and induced downregulation of MHC class I molecules H2-D1 and H2-K1 in the tumor cells." (PMID 27148255, 2016). "Using estrogen-supplemented oophorectomized mice bearing MMTV-PyMT mammary tumors, further studies demonstrated that inhibition of either CCL2 or CCL5 using blocking antibodies resulted in reduced macrophage infiltration and reduced tumor growth." (PMID 26884646, 2016). "Our PCR array data showed that both M1-related genes (Ccl2, Ccl3, Ccl4, Ccl5, Il12b, Il1b and Ccl1) and M2-related genes (Il10, Tgfb2 and Il1rn) were significantly upregulated in NM11-shsST2 tumours compared with NM11-shCont tumours." (PMID 27882929, 2016). "In conclusion, reduction in plasma CCL2 in patients with CRCLM treated with EPA predicts better clinical outcome and a specific tumor gene expression profile." (PMID 27058904, 2016). "In a complex chemokine network in human cancers, CCL2 localizes to epithelial areas of the tumor, and CCL5 localizes with tumor-infiltrating leukocytes." (PMID 27166185, 2016). "CCL2 and its receptor CCR2 are the chemokines largely participating in tumor microenvironment by regulating macrophage mobilization and infiltration, and also by recruiting inflammatory monocytes from bone marrow to peripheral sites of inflammation." (PMID 26701209, 2016). "While CCR2+ myeloid cells contribute to tumor cell metastasis, CCR2+ endothelium is activated by CRC-derived CCL2, which increases vascular permeability and cancer cell extravasation through the JAK2-Stat5 and p38MAPK pathways." (PMID 27136535, 2016). "In xenograft tumors derived from CCL2‐secreting 786‐O cells, CCL2NA treatment suppressed tumor growth accompanied with a decreased MVD, and these effects were comparable to those with bevacizumab treatment." (PMID 27666332, 2016). "The tumor secretes chemokines CXCL8, CCL2, IL-1, and TNF-α that recruits macrophages and suppressive CD4+CD25+CD127lowFOXP3+ Tregs to the tumor site." (PMID 25972872, 2015). "While immunohistochemical staining of primary (localized) PCa tumors showed CCL2 levels correlated with Gleason score and tumor stage, analysis of metastasized CRPC sample data sets in Oncomine reveals reduced CCL2." (PMID 26327448, 2015). "Tumor infiltration of TAMs is often mastered by the Ccl2 chemokine that attracts Ccr2+ monocytes circulating in the blood, but in this study the expression of Ccl2 mRNA and its encoded protein MCP-1 in tumors were not modulated by treatment and hence cannot explain the effects on TAMs." (PMID 26673090, 2015).
tumor (continued). "Since then, additional tumor-derived factors (LOX, CCL2, and VCAN) have been shown to stimulate recruitment of bone-marrow-derived cells (BMDCs) and hence contribute to formation of the premetastatic niche in a similar manner." (PMID 26770016, 2015). "This was associated with a transient expansion of myeloid cells and increased cytokines with myelogenic potential including C-C chemokine ligand 2 (CCL2), interleukin-6 (IL-6), and VEGF-A that primed the environment for tumor growth." (PMID 26459393, 2015). "The tumor CMT-93 cells used here, like many human tumor cells express the chemo-attractant monocyte-1 protein (MCP-1/CCL2) and many bone marrow derived cells were attracted by the tumor." (PMID 26299614, 2015). "For example, CCL2/MCP-1 expression is induced in healthy donor mesenchymal stromal cells by co-culture with malignant FL cells, possibly via secretion of TNF by the tumor cells." (PMID 25941795, 2015). "This response was especially prominent when PDT (60 μM ZnPC-ETLs) induced complete tumor cell death, at which point pro-inflammatory signaling by tumor cells was abrogated (TNF-α and CCL2)." (PMID 26307977, 2015). "We have previously demonstrated that FL-MSCs overexpressed CCL2 in response to B-cell derived TNF and identified here IL-8 as another marker of tumor-educated MSCs." (PMID 26158216, 2015). "In a recent study, anthracyclin chemotherapy induced Ly6Chi CD11c+ cells at the tumor site by an ATP- and CCR2/CCL2-dependent mechanism." (PMID 26635798, 2015). "Among other chemokines and cytokines secreted at tumor sites by immune cells, SDF1, a potent chemo-attractant for endothelial cells, the chemokines CCL2, CXCL8, CXCL1, CXCL13, and RANTES contribute to the neo-angiogenesis." (PMID 28536400, 2015). "TNF-α (and IL-1β) induced the release of CCL2, CXCL8 and CCL5 by MSCs and CAFs generated by prolonged stimulation of MSCs with Tumor CM of MDA-MB-231 and MCF-7 cells." (PMID 25928089, 2015). "Next, we measured mRNA levels for IFN-γ, FasL, CCL2, and CXCL9 in the lung from tumor-bearing WT and iNOS-KO mice after GalCer administration." (PMID 26496031, 2015). "Therefore, we plan to investigate whether administering a mixture of leptin inhibitor together with a CCL2 inhibitor to tumor bearers will result in a better approach to reduce tumor progression and adipose tissue inflammation in this tumor model with DIO mice." (PMID 25599228, 2015). "Taken together, our findings suggested that the chemokines CCL2, CCL3 and CCL14 not only regulated MO/MΦ chemoattraction, but also controlled mMΦ proliferation within the MM tumor bed and induced MΦ polarization toward mMΦs." (PMID 26155942, 2015). "Previous studies demonstrated that tumor cells migrate into bone marrow in response to various chemokines and cytokines such as CXCL12, CCL2, and IL6, which are released by MSCs." (PMID 25883937, 2015). "Cancer metastasis is amplified by CCL2 and FSTL1, which are abundantly produced by both the sMSCs and the metastatic tumor cells within the tumor microenvironment." (PMID 25883937, 2015). "We further confirmed increased expression of PD-1, PD-L1 with CCL2 and CXCL1 in the tumor lysaytes of 2cKO mice as compared with syngeneic counterparts." (PMID 26573233, 2015). "Several cytokines and chemokines are produced by macrophages in the tumor microenvironment including IL-8, stromal-derived factor-1 (SDF-1) and CCL2." (PMID 26317041, 2015). "In addition to confirming the presence of leptin, fatty acids and CCL2, we identified several other paracrine molecules produced by the crosstalk among the three cell types that also exhibit chemotactic, pro-angiogenic, pro-inflammatory, and tumor-promoting functions." (PMID 25599228, 2015). "We show that CCL2 is the main molecule produced in this DIO tumor model with chemotactic and tumor-promoting activities, followed by the chemokine IP-10 (CXCL10) and by the pro-tumor pro-inflammatory cytokine IL-6." (PMID 25599228, 2015).
tumor (continued). "We found that the sMSCs prepared either in vitro or in vivo specifically produce ANGPT2, CCL2, CCL3, and FSTL1, and most powerfully affect tumor behavior and host immunity by using these molecules (unpublished data except CCL2)." (PMID 25883937, 2015). "In whole tumor tissue samples, we found higher TNF-α and CCL2 gene expression, along with higher CCL3 protein expression in cachectic patients, as compared to WSC." (PMID 26732354, 2015). "This PTM reduces the binding affinity of CCL2 to its receptor CCR2, affecting drastically tumor homing of CD8+ T lymphocytes." (PMID 24605112, 2014). "Subsequently, splenic Ly6Chigh monocytes are recruited to the tumor in a CCL2/CCR2-dependent fashion, where they contribute significantly to the TAM pool and tumor progression." (PMID 24723924, 2014). "Monocyte chemotactic protein 1 (MCP-1/CCL2) is a 76–amino-acid peptide secreted by fibroblasts, endothelial and epithelial cells, monocytes, and various tumor cells." (PMID 24586454, 2014). "CCL2 and CCL5 have been also suggested to shift the balance in the tumor microenvironment towards increased vascularity." (PMID 25165728, 2014). "CAFs produce CCL2, CCL5, CCL7, CXCL8, and CXCL14 and these chemokines promote tumor progression mainly by enhancing the motility of tumor cells." (PMID 24966464, 2014). "TAM originate from circulating monocytes which are recruited to the tumor site and programmed by tumor-derived factors such as colony-stimulating factor-1 (CSF-1), vascular endothelial growth factor A (VEGF-A) and CC chemokine ligand 2 (CCL2)." (PMID 24634660, 2014). "Different C-C motif ligand-chemokines (CCL) and C-X-C motif ligand chemokines (CXCL), such as CCL2, CCL7, CXCL1 and CXCL6, are also potent stimulators of pro-malignant features, such as tumor cell proliferation, migration and invasion, as well as angiogenesis." (PMID 24887580, 2014). "In CCR2−/− mice, the accumulation of MDSCs is significantly reduced, indicating that MDSC infiltration in the tumor is dependent on the chemokine GPCR CCR2 and its ligands, mainly CCL2 produced in the tumor." (PMID 25110692, 2014). "Overall, a high CCL2 expression level is correlated with a worse outcome in many cancer types, suggesting that CCR2+ inflammatory monocytes often function as tumor-promoting cells." (PMID 24723924, 2014). "This accumulation of macrophages occurs within hypoxic areas of the neoplasm that contain necrotic tissue and is mediated primarily by the CC chemokine, CCL2/monocyte chemoattractant protein-1/MCP-1." (PMID 23847541, 2013). "Within the tumor microenvironment, COX-2, prostaglandins, SCF, CCL2, GM-CSF, M-CSF, VEGF, CXCL5, calcium-binding pro-inflammatory proteins S100A8 and S100A9, and TNF, all favor the chemotaxis and expansion of immunosuppressive MDSCs." (PMID 23577028, 2013). "CCL2, an MDSC-attracting chemokine, was reduced in the tumor microenvironment, and MDSC were decreased both in the bone marrow and the tumor microenvironment." (PMID 23508517, 2013). "IHC analysis confirmed markedly increased CCL2, pSTAT3, EMT markers (MMP9 and Snail) and F4/80-positive macrophages in TRAMP-C1 siAR tumours, and the treatment with CCR2atg significantly reduced these up-regulated markers." (PMID 23982944, 2013). "MCP-1/CCL2 can also stimulate macrophages to secrete urokinase-type plasminogen activator (uPAR) and MMP-9, both of which have the ability to remodel the tumor ECM." (PMID 24314323, 2013). "Among the chemoattractants, CCL2 (formally referred to as monocyte chemoattractant prorein-1, MCP-1) is suggested to be important in tumor progression." (PMID 23673510, 2013). "Treatment of tumor cells with EGCG resulted in a significant decrease of both CSF-1 and CCL-2 expression." (PMID 24044575, 2013). "CCR2 expression by Sirpα+ cDCs prompted us to examine the function of Sirpα+ cDCs in tumor-bearing mice, because CCR2 ligands, particularly CCL2, are abundantly expressed in tumor-bearing mice." (PMID 22815949, 2012).